CRP (C-reactive protein)
Diseases named in the same sentence as CRP in open-access papers (continued):
Sharing a sentence is not in itself a finding about the gene and the disease.
infection (continued). "Our simple new scoring system for mortality prediction, based on readily available clinical and laboratory data, including procalcitonin, C-reactive protein, and lactate, can be used in emergency departments for cancer patients with suspected infection." (PMID 34439240, 2021). "On the contrary, the animals that received a high dose of 50 CFU, displayed higher than baseline CRP values (> 5 μg/mL) as early as 3 weeks post infection." (PMID 34484203, 2021). "Recently, in community-acquired pneumonia, NLR has been found to have more prognostic power than known infection markers, such as CRP, white blood cell count, and neutrophil count." (PMID 33315348, 2021). "Though ESR and CRP are traditional inflammatory indicators that are widely used to evaluate postoperative infections, they can be influenced by surgical intervention." (PMID 34030692, 2021). "When the general conditions of patients improved, the values of infection biomarkers, especially IL-2R, IL-6 and CRP, significantly decreased." (PMID 33542448, 2021). "While high CRP levels were already reported during inflammation processes, our results indicate that CRP can be transported to other cells through EVs, thus driving the infection’s inflammatory effect." (PMID 33693030, 2021). "CRP is a typical acute phase protein and is mainly produced by hepatocytes in response to inflammation, tissue damage, and infection." (PMID 33406501, 2021). "Elevated CRP level is a marker of an acute inflammatory response, and elevated lymphocyte levels are an indicator of infection with viruses and other pathogens and immune function." (PMID 34930966, 2021). "We assessed systemic inflammation through levels of C-reactive protein (CRP), and measured procalcitonin as an approximation of infection." (PMID 34183060, 2021). "The relative changes in SAA and CRP concentrations in the four clinical types of patients exhibited higher ranges than those in infection-mediated clinical biomarkers." (PMID 34205852, 2021). "For SLR, CRP was the strongest independently associated factor, followed by age, blood glucose level before FDG-PET/CT, and having a cardiovascular focus of infection." (PMID 33106925, 2021). "The coregulated protein serum amyloid alpha 1 (SAA1) shows highly similar fold changes upon infection and is likewise covered, resulting in a more inclusive reflection of an individual’s inflammation status than the routine assessment of CRP alone." (PMID 33444735, 2021). "CRP is frequently used in the clinical setting as a screening marker of infection and/or inflammation." (PMID 33815405, 2021). "CRP is an acute-phase protein, which is mainly produced when acute inflammation or infection occurs." (PMID 34340677, 2021). "Characteristic features, occurring more frequently in the antibiotic treated patients included fever, preceding infection, elevated CRP and WBC." (PMID 33950404, 2021). "Many of the clinicians identified markers of infection (such as CRP or white cell count in a full blood count) as desirable, although some expressed reservations." (PMID 34911451, 2021). "Preoperative high-sensitivity-CRP (hs-CRP) to alb ratio has previously shown to predict independently signs of severe infection in nephrolithotomy." (PMID 33740951, 2021). "However, CRP levels that normalize at least once during the interim period may suggest that a successful PJI treatment is likely, although the presence of a low-grade infection or other underlying factors may prevent the CRP levels from consistently falling below 10 mg/L during this period." (PMID 34856956, 2021). "Often CRP tests were used as a communicative aid to reassure patients of the viral origin of the infection or to prove the effect of a commenced treatment." (PMID 34205866, 2021). "CRP is a systemic marker of inflammation, and it increases in the peripheral blood following infection, trauma, and/or tissue damage." (PMID 34943627, 2021).
infection (continued). "The mediators of acute inflammation and infection, such as CRP, IL-6, and PCT, have long been involved in the pathophysiology of critically ill patients and are routinely used for diagnostic, prognostic, and treatment monitoring in the ICU." (PMID 34749673, 2021). "Our findings contrast with self-reported practice in a recent survey of 147 intensivists from 91 ECMO centers across 25 countries, which identified that rising CRP or PCT were the most commonly used criteria to diagnose infection." (PMID 35155322, 2021). "A widespread immunochemical marker of inflammatory conditions is C-reactive protein (CRP), which serves as a first-line marker of infection, inflammation or tissue damage in routine laboratory medicine." (PMID 33669013, 2021). "Serum C-reactive protein (CRP) is an acute-phase reactant produced by the liver in response to infection, inflammation, and neoplasm." (PMID 34572314, 2021). "Patients with a lower lymphocyte count or higher C-reactive protein, neutrophil count, and neutrophil-to-lymphocyte ratio presented with a decreased eGFR during their early infection phase." (PMID 34069451, 2021). "Exclusion of infection as a contributing factor to the elevated serum CRP level cannot be provided for every patient." (PMID 34887479, 2021). "CRP levels decreased significantly in all of these patients after 2 weeks (range: 38.07–90.59%), and they all remained infection free." (PMID 34856956, 2021). "When presence of infection is suspected, work-up with C-reactive protein level and PET-CT are performed." (PMID 34074206, 2021). "CRP, mainly synthesizedin the liver upon an acute inflammatorystimulus, has been found to be a potent biomarker of infection andpathological cardiovascular events." (PMID 34056444, 2021). "WBC counts and neutrophil ratios and CRP are easily affected by other factors, such as coinfection with bacteria, the use of glucocorticoids, and the duration of infection." (PMID 34655117, 2021). "Laboratory tests showed elevated infection parameters (C-reactive protein [CRP] 105 mg/l, leucocytes 22.5 10^9/l), liver enzymes and N‐terminal pro-brain natriuretic peptide (NT-pro-BNP: 3532 pg/ml)." (PMID 34403067, 2021). "In the D+T− group, receiver operating curve (ROC) analysis of PCT and CRP levels on the day of secondary infection yielded area under the receiver operating curves (AUROC) of 0.50 and 0.57, respectively." (PMID 34353339, 2021). "An Indian research piece reported that CRP was useful to establish the diagnosis of infections, and serial CRP monitoring was necessary in order to evaluate the response to antibiotic therapy in children with FN." (PMID 34943282, 2021). "The available laboratory test for screening general infection includes C-reactive protein (CRP), white blood cell count (WBC), neutrophil-lymphocyte count ratio (NLCR), procalcitonin (PCT), and so forth." (PMID 34692716, 2021). "Patients with infections of the CF exhibited the lowest leukocyte (8.0 × 109/L) and CRP levels (36.9 mg/dL)." (PMID 33532496, 2021). "Apart from being markers of systemic inflammation, CRP and fibrinogen are acute-phase protein induced by proinflammatory cytokine contributing to host defense against infection." (PMID 33613636, 2021). "As CRP is typically determinedin conjunction with low-abundance infection biomarkers, the dilutionof the serum poses a serious practical problem." (PMID 34056444, 2021). "In this pathology, a series of classic biomarkers have been widely used for the diagnosis of infection and to evaluate the prognosis of the disease: C-reactive protein (CRP) and procalcitonin (PCT)." (PMID 34200950, 2021). "Firstly, we found that eosinophil counts and ratios significantly and inversely correlated with infection markers, ie, C-reactive protein (CRP), procalcitonin (PRO), and ferritin (FER)." (PMID 33589865, 2021). "The data indicate that endogenous murine WT CRP also participated, along with E-CRP-1, in protecting mice against infection in our animal model." (PMID 33117400, 2020).
infection (continued). "They analysed the effectiveness of CRP as a test in determining the eradication of infection by using the area under a receiver operator characteristic (ROC) curve (AUC)." (PMID 32089975, 2020). "Surprisingly, in one mouse model, CRP triple mutant protected mice against infection despite being unable to bind to PCh, suggesting that complement activation by CRP-PCh complexes was not required for protection." (PMID 32903624, 2020). "C-reactive protein (CRP) is an acute-phase protein synthesized in the liver in response to infection or inflammation." (PMID 33061986, 2020). "ROC curves were plotted for the predictive ability of MRP8/14 and CRP to discriminate between acute KD and an infection." (PMID 32775314, 2020). "More than half (59%) of the subjects had glutamine deficiency and this correlated significantly with biochemical markers of infection/inflammation (CRP level) and illness severity (SOFA and APACHE II scores)." (PMID 32028696, 2020). "The exclusion of participants with CRP levels of >10 mg/l at any point minimised potential confounding by chronic inflammatory conditions or current infection." (PMID 31707310, 2020). "They found that the ESR remained persistently elevated in 37 knees (54%), and the CRP remained elevated in 14 knees (21%) where the infection had been controlled." (PMID 32887615, 2020). "Among these indexes, CRP is a classical acute-phase protein displaying a rapid and pronounced rise in its plasma concentration in response to acute inflammation, infection, and tissue damage." (PMID 33036573, 2020). "A significant difference in the treatment time between the two groups was identified in the curve of cumulative suspension of antibiotics, with less exposure in the CRP group only for the index infection episode (p = 0.007)." (PMID 32487263, 2020). "In univariate logistic regression analysis, the LMR, monocyte count, NLR, CRP, CTP, MELD, and AAR were associated with the presence of infection." (PMID 32155772, 2020). "Regarding the laboratory tests results, the subtle abnormalities of leucocyte count, neutrophils ratio, lymphocytes ratio, and C-reactive protein of some cases suggested the infection history and inflammatory responses." (PMID 33371153, 2020). "We consider that an NLR value ≥5 can be a better marker than CRP, having the capacity to predict the presence of infection, at a lower cost." (PMID 32751302, 2020). "Of the infections with fast-growing bacteria, 17% showed a CRP level below 5 mg/L, and of those with slow-growing bacteria, 61.5% showed a normal CRP level (p < 0.001)." (PMID 32095896, 2020). "The level of CRP increases up to 1000-fold within a few hours in response to inflammatory stimulation such as trauma, burn, cancer, and various infections or inflammatory diseases." (PMID 32220241, 2020). "Methods for assessing postoperative infection that are widely used include monitoring serum C-reactive protein (CRP)." (PMID 33059760, 2020). "Present study indicates that the use of CRP for surveillance of infections in the very early period after liver transplantation is characterized by similar AUC, similar specificity and NPV, similar or slightly higher PPV, but remarkably lower sensitivity." (PMID 32127631, 2020). "Patients with CV-A10 and CV-A6 infection had a higher level of C reactive protein and a slightly lower level of platelet count than EV-A71/CV-A16 infected patients." (PMID 32804980, 2020). "Parental understanding of CRP is recently increasing and caregivers tend to consider higher CRP values as a sign of severity and a strong marker of infection, especially in recurrent illnesses." (PMID 32637387, 2020). "Comparable to our results, a previous study has detected an increase in CRP in Mycoplasma pneumoniae infection after trauma, inflammation, and tissue damage, especially in infections with bacteria." (PMID 33240679, 2020).
infection (continued). "Routine diagnosis of periprosthetic suspected infection includes blood test, erythrocyte sedimentation rate, C-reactive protein level, bacterial and fungal cultures, and pathology examinations, which were performed." (PMID 32481454, 2020). "Laboratory markers of inflammation and infection including C-reactive protein (CRP) (65% (95% confidence interval (CI) 56–81%)) were elevated, while lymphocyte counts were decreased (63% (95% CI 47–78%))." (PMID 32668763, 2020). "The C-reactive protein (CRP) is a protein secreted by the human liver in response to inflammation due to an infection or any tissue injury and is used as a laboratory marker to diagnose neonatal bacteraemia." (PMID 32750089, 2020). "CRP, an acute inflammatory protein, plays important roles in inflammatory processes and host responses to infection." (PMID 33239109, 2020). "Compared to NLCR, both PCT and CRP levels showed good differential ability between the non-infection and HAP groups." (PMID 32527243, 2020). "White blood cell (WBC) levels, neutrophil to lymphocyte ratio (NLR), platelet to lymphocyte ratio (PLR), and C-reactive protein (CRP) levels are the commonly used inflammatory markers for differential diagnoses of infection in the ED." (PMID 33019760, 2020). "The first validation cohort confirmed the predictive value of MRP8/14+CRP to discriminate acute KD patients (n = 26) from those with infections (n = 150), with an AUC of 0.78." (PMID 32775314, 2020). "It is well known that CRP is an acute phase reactant synthesized in liver in response to infection or inflammation and its serum concentration can increase up to 1000-fold during acute inflammatory events and correlated well with severity of infection." (PMID 32814554, 2020). "A significant increase in both PCT and CRP levels was observed in case of the occurrence of a secondary infection." (PMID 33023606, 2020). "It has become apparent that any kind of tissue damage induced by infection, trauma, or tumor necrosis will result in a pathological increment of the blood CRP level." (PMID 31936329, 2020). "The level of human CRP is also increased 1000-fold within 24–48 h in response to infection, inflammation, and tissue damage." (PMID 33374119, 2020). "Clinicians must cautiously interpret CRP levels and rule out the possibility of pathogen invasion and other systemic inflammation diseases, while a CRP level <33 mg/L is common in refractory febrile children with infection." (PMID 32432067, 2020). "Recently, NLR showed greater prognostic power than that of traditional inflammatory biomarkers of infection (CRP, total leukocyte count, and neutrophil count) in youth and adults with acute community-acquired pneumonia." (PMID 32083213, 2020). "Some previous studies had mentioned that ESR and CRP were representative serologic values for diagnosing infection." (PMID 32334610, 2020). "C-reactive protein is an essential element of innate system defense that regulates the inflammatory response and acts as a safeguard against infection." (PMID 32368278, 2020). "The CRP level increases significantly during infection and inflammation and this increase develops in correlation with the severity of the infection or inflammation." (PMID 30522831, 2020). "Univariate analysis indicated that male sex, higher CRP levels and higher Pitt scores were associated with MDRO colonization or infection." (PMID 32430043, 2020). "The patients with higher infection index (such as CRP, PCT, ESR, SAA, IL-6) were prescript antibiotics for 5–7 days in addition." (PMID 32208917, 2020). "Although CRP and leukocyte count are sometimes regarded as infection and inflammatory parameters that are jointly elevated, these results illustrate that this is not always the case." (PMID 32030452, 2020). "IL-6ascites performed better in “ruling out” apparent infections on admission to ICU than CRP, PCT, or IL-6serum." (PMID 32899730, 2020).
infection (continued). "CRP, secreted by the liver in response to bacterial infections, is a parameter used to diagnose infection." (PMID 32243412, 2020). "The original idea for the intervention was to provide nursing home staff with a biomarker for severe infection (C-reactive protein as a point-of-care test) in addition to the dialogue tool." (PMID 32383679, 2020). "It is possible that CRP plays a general antibacterial role, as exemplified in studies that show CRP protecting mice against infection with Salmonella typhimurium also." (PMID 33117400, 2020). "Several of the physicians had experienced PCT as an additional tool to traditional infection markers, such as C-reactive protein (CRP) and leukocytes." (PMID 32677903, 2020). "We determined for the first time that the CRP level also has predictive value for MDRO colonization or infection." (PMID 32430043, 2020). "Chronic inflammation is also a simple marker of other diseases, and circulating levels of CRP or IL-6 are easily influenced by infection and the anti-infectious medication use." (PMID 33202561, 2020). "CRP levels can be used as an indicator of low-grade inflammation in infections and chronic diseases." (PMID 32695177, 2020). "In general, PCT increased rapidly within 2-3 hours, peaked within 6-8 hours, lasted for 12-48 hours, and decreased rapidly in 2-3 days after infection control, while CRP increased significantly after 12 hours of inflammation." (PMID 33235597, 2020). "They concluded that the CRP is a more sensitive indicator of deep postoperative infection than plasma viscosity." (PMID 35236472, 2020). "CRP production in the circulation elevates its level in serum in response to various inflammations, infection, stress, trauma, surgery, tissue damage, cardiovascular disease, and neurological degeneration." (PMID 32992442, 2020). "The normal CRP concentration in human serum is 40 nM, and CRP concentration increases above 666 nM (840 mg/L) in the case of inflammation and infection." (PMID 32443702, 2020). "There were numerous abnormal infection-related biomarkers in sera of the diabetic patients, hs-CRP, ESR, PCT, and IL-6 were beyond the normal range." (PMID 33071977, 2020). "CRP has been described as a candidate biomarker for active TB disease and also in other infections as well." (PMID 32470023, 2020). "It seems that male patients have more obvious symptoms of infection, of which the level of high hypersensitivity C-reactive protein and creatinine increased." (PMID 33332437, 2020). "There is some evidence that CRP and IL-6 levels remain relatively stable over time, and studies have often excluded participants with suspected infection." (PMID 31707310, 2020). "Levels of CRP spiked very early in infection and returned to normal by day 45, whereas the rise in IFABP and sCD14 occurred with slower kinetics and did not fully normalize to levels observed prior to infection." (PMID 31937782, 2020). "In MoM bearings, hypersensitivity reaction and aseptic inflammation can also generate purulent appearance (“pseudo-purulence”), along with joint pain, increased serum CRP, and other symptoms of suspected infection." (PMID 31641803, 2020). "Biochemical markers of infection and inflammation (elevated CRP and decreased serum albumin levels) and clinical scores of disease severity (elevated APACHE II and SOFA scores) were significant indicators of low plasma glutamine levels." (PMID 32028696, 2020). "The author concluded the CRP and IL-6 appears to be the most helpful combination for distinguishing between aseptic loosening and low-grade infection." (PMID 33008442, 2020). "Since E-CRP-1 does not bind to PCh, and hence cannot activate the complement system, these results indicated that the increased resistance to infection in E-CRP-1-treated mice was due to combined actions of E-CRP-1 and endogenous mouse WT CRP." (PMID 33117400, 2020).